IL17A (interleukin 17A)
Diseases named in the same sentence as IL17A in open-access papers (continued):
Sharing a sentence is not in itself a finding about the gene and the disease.
insomnia (6 papers, 2018 to 2025). A sleep disorder characterized by difficulty in falling asleep and/or remaining asleep. "Additionally, patients with AS receiving TNFi or anti-IL-17A therapy in a smaller multicentre study demonstrated significant associations between Functional Assessment of Chronic Illness Therapy – Fatigue and Insomnia Severity Index scores (P < 0.0001 and P = 0.0001, respectively)." (PMID 40584930, 2025). "Similar adjustments were performed for insomnia, and the association between insomnia and IP-10 and TNF-RII, as well as CRP, IFN-r, IFN-α2a, and IL-17A also remained statistically significant (P < .05 for all)." (PMID 33134822, 2020). "Changes in IP-10 and TNF-RII levels were associated with worsening of general fatigue (P = 0.03 and P = .02, respectively), and statistically significant associations were observed between insomnia and CRP, IFN-r, IFN-α2a, IL-17A, IP-10, and TNF-RII (P < .05 for all)." (PMID 33134822, 2020).
keratoconus (6 papers, 2011 to 2025). A degenerative, structural disorder of the eye, characterized by a cone-shaped protrusion of the cornea. "Values below the LLOQ were observed rarely: 12.5% (n = 6, three in each group) for IFN-γ, 4.17% (n = 2, both in the keratoconus group) for IL-17A, 2.08% (n = 1 in the control group) for TNF-α and never for the remaining cytokines." (PMID 40980981, 2025).
leptospirosis (6 papers, 2012 to 2022). A contagious bacterial infection caused by spirochetes of the genus Leptospira. "Earlier studies from Malaysia identified elevated levels of cytokines such as IL-6, IL-17A and IL-22 as potential prognostic biomarkers with IL-17A as the independent predictor for leptospirosis associated fatalities." (PMID 34666707, 2021). "Elevation of IL-17A together with the significant elevation of IL-21 and IL-23 suggests a possible involvement of Th17 cells in the immunopathogenesis of leptospirosis." (PMID 30123395, 2018). "While several studies have reported the presence of IL-17A in intracellular bacterial infections, only few studies have investigated the role of IL-17 in leptospirosis." (PMID 30123395, 2018). "IL-4, IL-6, IL-8, IL-10, IL-17A, and TNF-α levels in severe leptospirosis compared to mild disease, and an association between high IL-6, IL-8, IL-10 and fatal outcome." (PMID 26824356, 2016). "Furthermore, there was a thread of increase in IL-10 (30.68 pg/ml ± 33.2) and IL-17A (11.66 pg/ml ± 5.4) in the leptospirosis group compared to the healthy group." (PMID 30123395, 2018). "Significantly higher concentrations of IL-1β, IL-2, IL-4, IL-6, IL-8, IL-10, IL-17A, and TNF-α were found in sera of leptospirosis patients." (PMID 35927283, 2022). "Elevation of serum IL-10 and IL-17A levels and significant elevation of serum IL-21 (p=0.002), IL-23 (p=0.002), and TNF-α (p=0.039) were observed among leptospirosis patients compared to the healthy control group." (PMID 30123395, 2018). "The serum cytokine levels of IL-10, IL-17A, IL-21, IL-23, and TNF-α were investigated in 57 patients with leptospirosis and 12 healthy controls using a commercially available ELISA kit (Mabtech, Sweden)." (PMID 30123395, 2018).
male infertility (6 papers, 2021 to 2025). The inability of the male to effect fertilization of an ovum after a specified period of unprotected intercourse. "For instance, ureaplasma-induced IL-17A production has been implicated in respiratory and neurological complications in preterm neonates, while Ureaplasma urealyticum infection elevates seminal IL-17A levels, impairing sperm quality and contributing to male infertility." (PMID 41438744, 2025).
malnutrition (6 papers, 2018 to 2026). Inadequate nutrition resulting from poor diet, malabsorption, or abnormal nutrient distribution. "Noticeably, LP and LPi groups exhibited a significant increase in il-17A expression in the duodenum as a result of malnutrition (p < 0.03)." (PMID 34207946, 2021). "Protein levels of IL-17A (p < 0.05), IL-21 (p < 0.05), and IL-22 (p < 0.05) were significantly increased in the LP and LPi mice due to malnutrition." (PMID 34207946, 2021). "Increased levels of duodenal IL-17A, IL-21, IL-22, CXCL5 due to malnutrition—together with decreased levels of TNFα, IL-12, TGFβ and CXCL10 and elevated levels of IgA due to infection—revealed that the duodenum was sensitive to both variables and suggested local inflammation in malnourished animals." (PMID 34207946, 2021).
memory impairment (6 papers, 2015 to 2025). "Tibial fracture surgery promoted memory impairment, increased levels of IL-17A and IL-17A receptors, inflammatory factor production and BBB dysfunction." (PMID 30501622, 2018). "In this paper, we demonstrated that LPS could induce IL-17A expression in the CNS and that IL-17A Abs, which neutralize IL-17A, suppressed neuroinflammation via the inhibition of microglial activation in an LPS-induced in vivo model and ameliorated memory impairment." (PMID 26373740, 2015).
neuropathic pain (6 papers, 2015 to 2023). Chronic pain caused by damage to nerve fibers. "Similarly, high IL-6, IL-17A, and TNFα levels were observed in the serum of lumbar radiculopathy patient group compared with the neuropathic pain group, and Th17 was higher in the venous blood of lumbar radiculopathy patients group compared with the neuropathic pain group." (PMID 35309927, 2022).
neuropathy (6 papers, 2015 to 2025). A disorder affecting the nervous system that manifests with pain, tingling, numbness, and/or muscle weakness. "IL-17A exacerbates neuropathy via activating immune cells, creating pro-inflammatory micro-environments and increasing oxidative stress." (PMID 41264657, 2025). "During neuropathy, females displayed more profound Th17 specific responses (IL-17A) than males, both at the injured nerve and in the corresponding LSC." (PMID 31763376, 2019). "The present study established that the alternatively spliced FN-CS1 isoform contributed to the selective mechanical allodynia onset in a rodent neuropathy model by regulating a content of IL-17A-expressing (presumably, Th17) cells at the nerve injury site." (PMID 26337825, 2015). "Therefore, the absence of contralateral IL-17A does not prove a lack of T cell recruitment or their actions in contralateral neuropathy." (PMID 31763376, 2019).
oral squamous cell carcinoma (6 papers, 2018 to 2024). "We found that increased salivary concentration of IL-17A, IL-17F, and TNF-α is associated with advanced oral squamous cell carcinoma." (PMID 32855976, 2020).
palmoplantar pustulosis (6 papers, 2021 to 2026). A rare skin disease characterized by chronic eruption of sterile pustules on an erythematous and desquamative background, affecting the palms and soles, sometimes also the lateral aspects of hands and feet. "Anti IL-17A therapy may lead to type conversion, with reported cases more prevalent in women and varying in onset time, predominantly involving palmoplantar pustulosis." (PMID 38695018, 2024).
Pneumocystis infection (6 papers, 2014 to 2025). "As reported, IL-17A production during Pneumocystis infection is increased, and blockage of IL-17 caused a 10,000-fold increase in Pneumocystis murina load in the lung of mice compared with wide-type mice." (PMID 29887863, 2018). "Although previous studies have showed that Th17 cells were involved in the immunity responses against Pneumocystis infection and blockage of IL-17A caused higher Pneumocystis burden in WT mice." (PMID 29887863, 2018). "In addition, as shown in a previous study, Pneumocystis infection can induce both Th2 and Th17 responses, stimulate the secretion of IL-13 and IL-17A, and further facilitate the formation of inducible bronchus associated lymphoid tissue (iBALT) in a Cxcl13-dependent manner." (PMID 37359523, 2023). "However, the data of this study also demonstrated that IL-17A is not required for control of Pneumocystis infection, which is inconsistent with our present study." (PMID 31582901, 2019).
polyarthritis (6 papers, 2008 to 2024). "The IL-17A rs8193036 variant genotypes (CT/CC) were more common among the patients than controls, especially in those with polyarthritis (OR 1.93, 95% CI 1.11–3.36; p = 0.020)." (PMID 39125893, 2024). "Our results suggest that both IL-17A rs8193036 variant genotypes CT/CC and IL-17A rs2275913 variant genotypes GA/AA increase the risk of oligoarthritis and polyarthritis types of JIA." (PMID 39125893, 2024). "IL-17A rs2275913 minor allele A was more common in patients (OR 1.45, 95% Cl 1.08–1.94; p = 0.014) and especially among patients with oligoarthritis and polyarthritis than the controls (OR 1.61, 95%CI 1.06–2.43; p = 0.024)." (PMID 39125893, 2024). "In this combined group of oligoarthritis and polyarthritis, IL-17A rs2275913 minor allele A was more common than in the control group (p = 0.023 (OR 1.59; 95% C1 1.07–2.37)." (PMID 39125893, 2024). "It is tempting to speculate that some oligoarthritis or polyarthritis patients with the IL-17A rs8193036 variant genotype could benefit from IL-17 blocking." (PMID 39125893, 2024). "Interestingly, our results showed that IL-17A rs8193036 minor allele C is associated with an increased risk, especially for the polyarthritis type of disease." (PMID 39125893, 2024). "Interestingly, IL-17A rs8193036 C-allele was more frequent in the polyarthritis group than in the controls (p = 0.020, OR 1.93; 95% Cl 1.11–3.36)." (PMID 39125893, 2024). "Also, IL-17A rs2275913 minor allele A was identified as a risk factor for oligoarthritis and polyarthritis types of JIA." (PMID 39125893, 2024). "Extended oligoarthritis has basically the same disease features as polyarthritis but with a more gradual onset, and in line with this, among the oligoarthritis group, all patients with an extended type of oligoarthritis had the variant genotype type of both IL-17A rs8193036 and IL-17A rs2275913." (PMID 39125893, 2024). "The only significant difference found was between oligo- and polyarthritis patients, with the polyarthritis patients having higher IL-17A levels (p = 0.049)." (PMID 39125893, 2024). "In a further analysis where the patients with extended oligoarthritis (n = 7) were excluded, and the patients with persistent oligoarthritis (n = 44) and polyarthritis (n = 34) were compared, no statistical differences in the distribution of IL-17A polymorphisms were found." (PMID 39125893, 2024).
polycystic ovary syndrome (6 papers, 2017 to 2025). A disorder that manifests as multiple cysts on the ovaries. "In a study on polycystic ovary syndrome, it was found that the level of IL-17A in patients was negatively correlated with ADAMTS9." (PMID 38371936, 2024).
prediabetes (6 papers, 2018 to 2025). "The decreased IL-17A level and increased Cd36 expression in prediabetes mice indicated that the specific gut microbiota promoted the absorption of excess PA by disrupting the integrity of the intestinal mucous layer and regulating the expression of IL-17A and Cd36." (PMID 40878918, 2025). "Similar analysis in Indians showed significantly higher levels of inflammatory biomarkers like high-sensitive C-reactive protein (hsCRP), IL1β, IL13, IL17A, IL6, TNFα, and IAP in individuals with prediabetes compared to normoglycemic individuals." (PMID 33658065, 2021). "The only exceptions were interleukin 10 (IL10) and interleukin 17A (IL17A) levels, which were significantly lower in individuals with prediabetes." (PMID 33658065, 2021). "No significant variation of cytokines was observed between prediabetes and control group for IL-6, IL-10, IL-17A, IL-4, IL-8, IFN-γ, and TNF-α." (PMID 37457235, 2023).
reactive arthritis (6 papers, 2013 to 2025). Reactive arthritis (ReA) is an autoimmune disorder belonging to the group of seronegative spondyloarthropathies and is characterized by the classic triad of arthritis, urethritis and conjunctivitis. "Although it was reported that iNKT cells can suppress IL-17A production by γδ T cells in Salmonella enterocolitis–induced reactive arthritis, the mechanism involved was not elucidated." (PMID 36477357, 2022).
sarcoma (6 papers, 2016 to 2023). A usually aggressive malignant neoplasm of the soft tissue or bone. "Further studies are needed to examine the effect of IL-17A/IL-17R interaction on viability, migration and invasion of other human sarcoma cells lines, as well as of primary synovial sarcoma tissue." (PMID 26850593, 2016). "This study aimed to investigate the level of CD4+ T cells and forkhead box protein P3+ (FoxP3+) Treg cells, as well as T-cell-related-cytokines such as TNF-α, IFN-γ, IL-17A, and TGF-β1 in the peripheral blood of sarcoma patients." (PMID 36005179, 2022). "The regulation of immune response in sarcoma patients was also studied by measuring several cytokines (IFN-γ, TNF-α, IL-17A, and TGF-β1) produced by Con-A-stimulated T cells." (PMID 36005179, 2022). "The concentration of other plasma cytokines, namely, TNF-α, IFN-γ, and IL-17A in sarcoma patients and normal controls, could not be determined as these cytokines were lower than the detection limit of the ELISA kits." (PMID 36005179, 2022).
synovial sarcoma (6 papers, 2016 to 2025). "The aim of this study was to elucidate the mechanisms underlying IL-17A-induced MMP-3 expression in the human synovial sarcoma cells HS-SY-II." (PMID 26850593, 2016). "For example, both LL-37 and IL-17A were shown to induce the transcription of TNFα in human synovial sarcoma cells, and LL-37 with IL-1β was demonstrated to synergistically increase IL-8 production in airway epithelial cells." (PMID 40410820, 2025). "The present study aimed to investigate the effects of LL-37 alone and in combination with IL17A, on the mechanisms related to inflammatory arthritis pathogenesis in the human synovial sarcoma cell line, SW982." (PMID 31260471, 2019). "In the present study, we have explored the role of IL-17A in the MMP-3 expression of synovial sarcoma cell lines, HS-SY-II." (PMID 26850593, 2016). "Our preliminary findings provide a valuable insight how IL-17A may contribute to the pathogenesis of synovial sarcoma by stimulating MMP-3 expression." (PMID 26850593, 2016). "In the present study, we examined the molecular mechanism by which IL-17A-induced MMP-3 expression in synovial sarcoma cells and demonstrated that IL-17 could regulate the expression of MMP-3 through MAPKs-AP-1 activation." (PMID 26850593, 2016). "This similar manner was shown in our previous report using a human synovial sarcoma cell line, SW982, which was induced by a combination of IL-1β and IL-17A." (PMID 33799537, 2021).
urticaria (6 papers, 2017 to 2025). A vascular reaction of the skin characterized by erythema and wheal formation due to localized increase of vascular permeability. "It was found that urticaria was associated with higher concentrations of IL-6 and IL-17A and lower values of IL-18, IL-23, RANTES and IP-10." (PMID 36539847, 2022). "Contrary to previous work, we confirmed a positive correlation between IL-17A levels and CRP in all patients with urticaria." (PMID 36539847, 2022). "At day 90, only 3 of the patients with the extreme cytokine value had an AR; the patients with the highest levels of IL-10 and IL-17A experienced grade 1 toxicities (urticaria and AR, respectively), while the patient with the highest levels of CXCL9 experienced grade 3 urticaria." (PMID 29967609, 2018). "A preliminary report found increased IL‐17A expression in both lesional and nonlesional skin of CSU and significant improvement of the weekly urticaria activity score, but also in the severity and frequency of AE in all eight patients treated off‐label with secukinumab." (PMID 40685762, 2025).
Achalasia (5 papers, 2015 to 2025). A disorder of esophageal motility characterized by the inability of the lower esophageal sphincter to relax during swallowing and by inadequate or lacking peristalsis in the lower half of the body of the esophagus. "IL-17A-and IL-22-producing cells were the main cellular components of the inflammatory foci in achalasia tissue." (PMID 26078981, 2015).
allergic conjunctivitis (5 papers, 2018 to 2025). "In a recent mouse model of allergic conjunctivitis, stimulation and activation of the Th17 cytokines IL-17A and IL-17F, as well as the specific transcription factor RORγt, suggest that developmental enhancement can exacerbate Th2 dominant allergic inflammation in conjunctivitis." (PMID 39295864, 2024).
ANCA-associated vasculitis (5 papers, 2013 to 2021). "In ANCA-associated vasculitis, IL-17A and IL-21 are influenced by Th17 effector T cells and increased in PR3-ANCA vasculitis and elevated IL-17A levels are found in MPO-ANCA vasculitis." (PMID 33023023, 2020). "Higher levels of serum IL-17A, IL-23, MPO and Pr3-specific Th17 cells are present in subjects with ANCA-associated vasculitis." (PMID 25964886, 2015).
Atherosclerotic lesion (5 papers, 2014 to 2025). A lesion associated with atherosclerosis, a multifactorial and multipart progressive disease manifested by the focal development within the arterial wall of lesions, that ranges from the development of a fatty streak, plaque progression, and plaque disruption. "Although the exact role of IL-17A in CVDs is still debatable, aggregated IL-17- producing cells and enhanced IL-17A levels have been observed in atherosclerotic lesions." (PMID 33602246, 2021).
atrophic gastritis (5 papers, 2020 to 2026). "Elevated IL-17A levels are often observed in patients with AIG or gastric cancer and correlate with disease severity in mice with chronic atrophic gastritis, specifically causing caspase-dependent gastric organoid degeneration." (PMID 39193325, 2024). "pylori-infected patients without atrophic gastritis, IL-17A and IFN-γ levels showed a linear correlation with PG levels." (PMID 42157998, 2026). "As we wondered whether IL-17A could be abnormal in patients with IM/DYS, we further measured serum IL-17A in Helicobacter pylori patients with gastric intestinal metaplasia and gastric dysplasia, in non-atrophic gastritis Helicobacter pylori patients without IM/DYS and in healthy controls." (PMID 36980548, 2023).
autoinflammatory syndrome (5 papers, 2018 to 2025). A group of disorders of the innate immune system characterized by attacks of seemingly unprovoked inflammation without significant levels of either autoantibodies or autoreactive T cells more characteristic of autoimmune disease. "Elevated levels of IL-1β, IL17-A, and PAI-1 have been associated with various autoinflammatory syndromes and diseases." (PMID 37659022, 2023).
blastomycosis (5 papers, 2020 to 2024). Blastomycosis is a rare infection that may develop when people inhale a fungus called Blastomyces dermatitidis, a fungus that is found in moist soil, particularly where there is rotting vegetation. "An experimental mouse model of vaccination suggested that Th17 cells expressing IL-17A are the main driver for immunity against pulmonary blastomycosis by activating macrophages and neutrophils." (PMID 36177012, 2022).
chronic asthma (5 papers, 2014 to 2025). An asthma that is characterized by the development of persistent airway inflammation and recurrent attacks of breathlessness and wheezing, which vary in severity and frequency. "In airway biopsies retrieved from individuals exhibiting chronic asthma, IL-17F and IL-17A (two proinflammatory mediators vitally implicated in neutrophilic activation and bronchial restructuring) are markedly elevated." (PMID 40136649, 2025).